AKAP14 (A-kinase anchoring protein 14)
Description:
Binds to type II regulatory subunits of protein kinase A and anchors/targets them.
Synonyms: PRKA14; AKAP28
Tractability: No criterion of Open Targets' tractability assessment is met for any kind of drug.
Gene: Protein-coding gene on chromosome X (119,895,837 to 119,920,720, forward strand). Ensembl gene ENSG00000186471.
Subcellular location: Cytoplasm
Gene Ontology:
Molecular function: protein binding; protein kinase A regulatory subunit binding
Cellular component: axoneme; cAMP-dependent protein kinase complex; cytoplasm
Homologues: Orthologues: chimpanzee AKAP14 (99% identical), macaque AKAP14 (95% identical), dog AKAP14 (47% identical), rat Akap14 (42% identical), mouse Akap14 (40% identical), tropical clawed frog akap14 (31% identical), zebrafish si:dkeyp-81f3.4 (22% identical).